CHORDC1 (cysteine and histidine rich domain containing 1)
Description:
Regulates centrosome duplication, probably by inhibiting the kinase activity of ROCK2. Proposed to act as co-chaperone for HSP90. May play a role in the regulation of NOD1 via a HSP90 chaperone complex. In vitro, has intrinsic chaperone activity. This function may be achieved by inhibiting association of ROCK2 with NPM1. Plays a role in ensuring the localization of the tyrosine kinase receptor EGFR to the plasma membrane, and thus ensures the subsequent regulation of EGFR activity and EGF-induced actin cytoskeleton remodeling. Involved in stress response. Prevents tumorigenesis.
Synonyms: CHP-1; CHP1
Tractability: PROTAC: ubiquitination databases record sites on it; its protein half-life has been measured.
Gene: Protein-coding gene on chromosome 11 (90,200,429 to 90,223,077, reverse strand). Ensembl gene ENSG00000110172.
Subcellular location (Human Protein Atlas): Cytosol
Gene Ontology:
Molecular function: Hsp90 protein binding; protein binding; zinc ion binding; ADP binding; ATP binding
Biological process: centrosome duplication; protein folding; regulation of cellular response to heat; negative regulation of Rho protein signal transduction; regulation of centrosome duplication
Genetic constraint (gnomAD): Loss-of-function variants: 12 observed, 22.05 expected, observed/expected ratio (o/e) 0.54, 90% interval 0.35 to 0.88. The upper end of that interval is the gene's LOEUF score, 0.88, which puts it in group 3 of 6, group 1 being the genes least tolerant of losing a copy. Missense variants: 171 observed, 204.67 expected, observed/expected ratio (o/e) 0.84, 90% interval 0.74 to 0.95. Synonymous variants: 73 observed, 65.21 expected, observed/expected ratio (o/e) 1.12, 90% interval 0.93 to 1.36.
Homologues: Orthologues: chimpanzee CHORDC1 (99% identical), mouse Chordc1 (95% identical), guinea pig CHORDC1 (95% identical), pig CHORDC1 (95% identical), rabbit CHORDC1 (94% identical), macaque CHORDC1 (93% identical), rat Chordc1 (91% identical), dog CHORDC1 (88% identical), tropical clawed frog chordc1 (78% identical), zebrafish chordc1b (72% identical), zebrafish chordc1a (68% identical). Paralogues in human: ITGB1BP2 (48% identical).
Diseases named in the same sentence as CHORDC1 in open-access papers:
CHORDC1 is named in the same sentence as 10 diseases in open-access papers, as found by Europe PMC text mining. Sharing a sentence is not in itself a finding about the gene and the disease. The quoted sentences say what the papers report.
breast cancer (2 papers, 2017 to 2025). A primary or metastatic malignant neoplasm involving the breast. "Key genes had elevated protein levels in differentiated breast cancer cell lines, and elevated CHORDC1 expression was linked to a tendency towards a worse outcome in patients with ER+ breast cancer." (PMID 40808956, 2025). "Transwell assays revealed that decreased CHORDC1 expression could significantly hinder the invasion and migration of breast cancer cells." (PMID 40808956, 2025). "Here we show that NF-κB activation in breast cancer cells depends on the presence of the CHORDC1 gene product Morgana, a previously unknown component of the IKK complex and essential for IκBα substrate recognition." (PMID 29158506, 2017). "MTT and EDU assays revealed that the viability of ER+ breast cancer cells with CHORDC1 knockdown was lower than that of the corresponding negative control cells." (PMID 40808956, 2025).
bladder cancer (1 paper, 2024). "Furthermore, Kaplan-Meier survival analysis revealed that the higher expression of VAMP5, TIGIT, LCK, CHORDC1, CD27, and CACYBP was correlated with better outcomes in bladder cancer patients treated with immunotherapy." (PMID 39033098, 2024).
epidermoid carcinoma (1 paper, 2020). "In order to test if the function of CHP-1 in the EGFR signaling pathway is conserved in mammals, we inactivated the CHP-1 homolog CHORDC1 in human A431 epidermoid carcinoma cells, which express high levels of the wild-type EGFR and undergo a phenotypic switch in response to EGF stimulation." (PMID 32053105, 2020).
prostate carcinoma (1 paper, 2022). A carcinoma that arises from epithelial cells of the prostate gland. "PFDN4, when combined with SHC4 and CHORDC1, regulates extracellular vesicle secretion in prostate cancer." (PMID 36438659, 2022).
cancer (3 papers, 2020 to 2025). A tumor composed of atypical neoplastic, often pleomorphic cells that invade other tissues. "Chi-square test analysis of the connection between CHORDC1 expression and clinicopathological features in HMU Cancer Hospital cohort." (PMID 40808956, 2025).
infection (1 paper, 2020). The state of being infected such as from the introduction of a foreign agent such as serum, vaccine, antigenic substance or organism. "An important gene for growth during stress, CHORDC1 associated with post-infection growth rate was identified as a positional candidate gene, as well as other immune related genes, including VAV2, IL12B, DUSP1, and IL17B." (PMID 32849779, 2020). "Genes in these regions, including CHORDC1 and DUSP1 are important candidate genes for post-infection rate and viral load at 2 and 6 dpi, respectively, and could be crucial in the chickens’ response to NDV infection." (PMID 32849779, 2020).
tumor (1 paper, 2025). "Moreover, the roles of other model genes such as CHORDC1 and PHYHD1 warrant further experimental exploration, particularly in the context of tumor metabolism and immune escape." (PMID 40496864, 2025).
CHORDC1 also shares sentences with these, for which no sentence is quoted: chronic myelogenous leukemia, BCR-ABL1 positive (1 paper); myeloproliferative neoplasm (1); overnutrition (1).